KRAS (KRas proto-oncogene, GTPase)
Diseases named in the same sentence as KRAS in open-access papers (continued):
Sharing a sentence is not in itself a finding about the gene and the disease.
cancer (continued). "This is in accordance with human data indicating that KRAS mutations can be frequently observed in human pancreata with PanIN lesions being present, but without signs of invasive cancers." (PMID 34070180, 2021). "Accordingly, our study aimed to investigate the functional behavior of these KRAS and PIK3CA cancer-driver genes along with identifying the somatic mutations associated with the aggressive benign tumor in the developed immortalized endometriotic epithelial cell line, HMOsisEC10." (PMID 34202354, 2021). "However, SHP099 does not reduce the viability of B16F10 cells even when the cells are cultured in 2–20% Matrigel, under conditions that have revealed increased sensitivity to SHP099 in certain KRAS‐mutant cancer cells (Fig EV2E)." (PMID 34102002, 2021). "Similarly, studies have also shown that combined RAF-MEK inhibition would overcome ERK reactivation in KRAS mutant or wild type cancer lines, implicating this as a potential strategy for PDAC." (PMID 34805167, 2021). "Identifying the mechanisms by which cancer cells bypass their dependence on mutant KRAS may aid the development of treatment strategies that increase the efficacy of KRAS inhibitors." (PMID 34491463, 2021). "Therefore, KRAS independency induced by the activation of YAP1 signaling is related to the rewiring of metabolic processes in KRAS mutant cancers." (PMID 34680229, 2021). "Notably, SH‐BC‐893 was also more effective than leflunomide at producing a tubulated mitochondrial network in cancer cells with activated KRAS, a model system where leflunomide has been shown to have antineoplastic activity." (PMID 34231322, 2021). "Combined with MEK inhibitor (trametinib), BI-3406 showed effectiveness in KRAS-driven cancers." (PMID 34252937, 2021). "However, for the large number of cancers driven through non-G12C mutant KRAS (e.g., G12D and G12V), much work remains." (PMID 35024121, 2021). "Based on the WIG calculation, we found that the perturbation on KRAS has the highest impact on the EMT pathway, though the influence is not specific to EMT, which is reasonable as KRAS is a frequently mutated oncogene in cancer." (PMID 33968127, 2021). "Thus, identifying strategies to inhibit key players, such as KRAS, in this cancer type are necessary for novel alternatives." (PMID 33801965, 2021). "Twenty-eight of 42 recipient females (66%) had pulmonary metastases at the time of necropsy, and the co-expression of the nuclear GFP reporter is indicative for the sustained expression of oncogenic KRAS during the dissemination and metastatic growth of cancer cells." (PMID 34145248, 2021). "Indeed, it was shown recently that mutant KRAS can rewire the metabolic process of cancer cells by transcriptionally activating NRF2, leading to acquired chemoresistance that can be effectively targeted." (PMID 33672357, 2021). "Comparing the mutation status of cancer critical genes in PUMC-CRC1 with that in 19 commonly-used CRC cell lines, PUMC-CRC1 was a unique cell line with APC (p.T1493fs), KRAS (p.G12V) and SMAD4 (p.V506A) mutations, which enriches the diversity of CRC cell lines." (PMID 34162944, 2021). "In addition, we show that cancer cells harboring mutant KRAS have an advantage in lactate production." (PMID 33833221, 2021). "Cancers harboring mutations in the Kirsten rat sarcoma homolog (KRAS) gene have been associated with poor prognosis and lack of targeted therapies." (PMID 34845311, 2021). "It appears that monotherapy with RAF inhibitors is not efficient against cancers with KRAS mutations, suggesting that combination with other MAPK pathway inhibitors should be attempted." (PMID 34607583, 2021).
cancer (continued). "The KRAS protein could activate several signaling pathways to promote the proliferation, invasion, and migration of cancer cells." (PMID 34447748, 2021). "Notably, RAF and SRC are validated targets in RAS-mutant cancers, because RAF signals downstream of oncogenic KRAS, and SFKs drive cancer cell proliferation and survival." (PMID 33130216, 2021). "Mutant KRAS in ctDNA might be a more sensitive predictor of survival than the ELISA-based detection of cancer antigen 19-9 (CA 19-9)." (PMID 34607583, 2021). "As inhibiting KRAS directly is very challenging, approaches to disrupt downstream signaling pathways may be a better approach to treat these types of highly aggressive cancer." (PMID 35692861, 2021). "Finally, YAP1 activation is also described as a bypass mechanism to KRAS inactivation in cancers driven by oncogenic mutant KRAS signaling." (PMID 34685695, 2021). "Similarly, co-targeting MEK and SHP2, which is required for RAS activation, has provided clinical utility and impaired cancer cell growth in both in vitro and in vivo settings of KRAS-mutant pancreatic cancer and NSCLC and gastroesophageal cancer." (PMID 34946644, 2021). "twenty to thirty percent of all human cancers have RAS (KRAS-HRAS-NRAS) alteration." (PMID 34604242, 2021). "Growing evidence suggests that SOD1 plays important role in cancer, particularly KRAS-driven NSCLC." (PMID 33859191, 2021). "Here the authors investigate the possibility of selection of pre-existing cancer driver mutations during CRISPR-Cas9 knockout based gene editing and identify KRAS mutants that may confer a selected advantage to edited cells." (PMID 34764240, 2021). "In addition to its role in activating MAPK and AKT signaling, KRAS is known to mediate metabolic rewiring in cancer, and many studies have elucidated the mechanisms by which KRAS reprograms cellular metabolism to support tumorigenesis." (PMID 34947990, 2021). "Consequently, identification of new therapeutic targets for innovative treatment strategies tailored to KRAS‐mutant cancers still represents a pressing need." (PMID 34369083, 2021). "KRAS mutant (mut) cancers often exhibit poor drug responses and prognosis." (PMID 33574444, 2021). "The mechanisms of chemoresistance in KRAS-driven cancers are not well understood." (PMID 34496878, 2021). "Oncogenic KRAS is known to promote elevated ROS levels in cancer cells due to aberrant metabolism." (PMID 33859191, 2021). "Additionally, depletion of CRaf but not BRaf in KRas mutant mice resulted in an inhibition of downstream ERK phosphorylation, an additional finding emphasizing the role of CRaf in KRas-driven cancer." (PMID 34680208, 2021). "KRAS mutant cancers, particularly those harboring G12C activation, also appear to be particularly prone to adaptive resistance driven by receptor kinase signaling in response to KRAS G12C inhibitors or MEK inhibitors." (PMID 34071428, 2021). "In addition to this cell autonomous signalling, KRAS mutant cancer cells can also signal to adjacent fibroblasts to change their phenotype and function." (PMID 34298706, 2021). "In addition, the KRAS oncogene, a critical driver of multiple cancers, is also an important target for cancer therapy." (PMID 33663535, 2021). "However, the artificial cyclic peptide KS-58 enhanced anti-cancer activity in vitro and in vivo in KRAS G12D mutant tumors by blocking intracellular Ras-effector protein interactions." (PMID 35096591, 2021).
cancer (continued). "In summary, MEKi Trametinib treatment facilitated oHSV replication, which may be mediated by down-regulation of PKR phosphorylation in KRAS mutant cancer cells." (PMID 34578339, 2021). "Overexpression of GGH may be associated with dysregulation of multiple cancer-related gene pathways, including those involved in cell cycle regulation, cell motility, MAPK, STAT3, and KRAS signaling, and immune responses." (PMID 35082830, 2021). "In contrast, frequencies of druggable KRAS hotspot mutations do not appear to be age-related in any of the seven cancer types." (PMID 34788626, 2021). "Our data further reveal that SOD1 is localized in the nucleus, which sustains cancer cell growth by promoting hyperactive ribosome biogenesis through PeBoW complex-dependent pre-ribosomal RNA (rRNA) processing and ribosome biogenesis in KRAS-driven NSCLC." (PMID 33859191, 2021). "Interestingly, another kinase named STK33 was also previously found to be critical for KRas-dependent cancer cells." (PMID 34955846, 2021). "The UBE2D complex is critical to maintain KRAS protein stability, and targeting such a complex might be a unique strategy to degrade mutant KRAS to kill cancer cells." (PMID 33810518, 2021). "KRAS G12S is a hotspot oncogenic gain-of-function mutation, whereas the biological effect of SMAD4 P356L is unclear, although this mutation is recurrent in various cancers and is predicted to be oncogenic." (PMID 35008475, 2021). "The presence or absence of KRAS dependency is related to the heterogeneity of KRAS mutant cancers." (PMID 34680229, 2021). "KRAS is one of the most common mutant oncogenes in human cancers." (PMID 34134622, 2021). "KRAS mutations are cancer-specific and do not exist in normal tissues, constituting mostly driver mutations that are ideal vaccine and ACT targets due to their clonal nature." (PMID 35083149, 2021). "RMC-4630 is in a phase I clinical trial as a single agent (NCT03634982) and in a new clinical trial in combination with an ERK inhibitor, LY3214996, for the treatment of patients with metastatic KRAS-mutant cancers (NSCLC, CRC and pancreatic cancer) (NCT04916236)." (PMID 34742312, 2021). "However, oncogenic KRAS plays a profound immunosuppressive role in cancer development and maintenance." (PMID 33674596, 2021). "During Kras-driven PDAC in mice, ferroptotic cancer cells promote the release of damage-associated molecular patterns (DAMPs) such as 8-hydroxy-2ʹ-deoxyguanosine (8-OHG) and KRAS-G12D protein, leading to macrophage polarization and subsequent pancreatic tumor growth." (PMID 34796174, 2021). "Notably, interference with nucleotide biosynthesis resulted in glutamine deprivation in KRAS-driven cancer cells and thus lead to S-phase cell cycle arrest and DNA replication stress." (PMID 34123854, 2021). "Contaminants included the cancer genes KRAS (2 samples, including one sample identified by manual review), STAG2 (35 samples), DDX58 (25 samples; DDX58 encodes RIG-I), and SNAP25 (9 samples), some of which can be traced to other projects from the same laboratory." (PMID 34952565, 2021). "PD-L1+ tumors were more frequent among KRAS mutated than wildtype cancers (26% versus 18%, respectively) (data not presented)." (PMID 34413420, 2021). "However, lonafarnib and tipifarnib disappointingly failed in clinical trials against KRAS-mutant-driven cancers." (PMID 34200676, 2021). "However, with more studies various new strategies have been identified to target KRAS for cancer therapy." (PMID 33801965, 2021).
cancer (continued). "Patients with cancers with mutations in RAS (HRAS, KRAS, and NRAS) had an overall response rate of 31% compared to a response rate of 32% in patients with RET-mutation positive disease with no survival benefit observed in patients with tumors lacking both RET and RAS mutations." (PMID 34489865, 2021). "This is consistent with KRAS-mutant CRCs being resistant to rapalogues, and other therapeutics and highlights the unmet need for effective therapies against KRAS-mutant cancers." (PMID 34895463, 2021). "Targeting HSP90 has shown therapeutic potential in KRAS-mutant cancer models." (PMID 34858498, 2021). "Analysis of the correlation between CCO immuno-genotype and TIM phenotype revealed that the TIM phenotype was associated with microsatellite instability, Wnt/β-catenin signaling, APC/KRAS mutations, and the unfolded protein response pathway linked to the FBXW7 mutation in cancer cells." (PMID 34256801, 2021). "A related study established that stimulation of mTORC1 with amino acids increases oncogenic H-Ras- but decreases K-Ras-nanoclustering via a phosphatidic acid-dependent mechanism downstream of SREBP1, with attendant consequences for spheroid growth of HRAS and KRAS mutant cancer cells." (PMID 33544116, 2021). "The results provide evidence that the malignant phenotype of KRAS knockout cancer cells is stable." (PMID 33674596, 2021). "This indicate that ubiquitination may represent a new therapeutic approach for the treatment of KRAS-mutant cancer." (PMID 34947990, 2021). "We describe CCT3833, a new drug that inhibits both RAF and SRC, which may be effective in KRAS-mutant cancers." (PMID 33130216, 2021). "Therefore, in patients with KRas and BRaf mutant cancers, immune checkpoint blockade has presented as an additional avenue of treatment to consider and has even produced positive results in patients with these mutations." (PMID 34680208, 2021). "While previous strategies to block KRAS oncogene therapeutically have focused on counteracting its growth-promoting role in cancer, we show that oncogenic KRAS plays a profound immunosuppressive role in cancer maintenance." (PMID 33674596, 2021). "Collectively, our findings raise the question of whether macropinocytosis blockade can be envisaged in a subset of WT KRAS cancer cells." (PMID 34112916, 2021). "With a near 100% KRAS mutation frequency, PDAC is considered the most RAS-addicted of all cancers." (PMID 33537098, 2021). "Targeting KRAS protein has been one of the toughest challenges in cancer treatment research." (PMID 33928034, 2021). "We observed that most of the cancer cells with the wild types of both KRAS and BRAF still exhibit resistance to SHP2 inhibition, which cannot be fully explained by the p-SHP2 levels, indicating an unknown mechanism for the resistance." (PMID 34790119, 2021). "The KRAS, NRAS and HRAS oncogenes are mutated in approximately 30% of all human cancers." (PMID 33924486, 2021). "The clinical benefit of small-molecule EGFR inhibitors on KRAS-mutant cancers is context-dependent." (PMID 34607583, 2021). "Thus, while effector pathway inhibition appears to be the most promising therapeutic strategy for targeting KRAS mutant cancers, significant challenges remain." (PMID 33917906, 2021). "Thus, SHP2 inhibition, which links RTKs to the RAS–RAF–MEK–ERK and RAS–PI3K–AKT–mTOR pathways, will be ineffective in KRAS-mutant or BRAF-mutant cancer cell lines." (PMID 34790119, 2021). "In addition, down-regulation of PKR and STAT1 mRNA levels was also observed in KRAS mutant cancer cells when combined treatment performed." (PMID 34578339, 2021). "Although IL-10 and TGF-β can induce a shifting of macrophages towards the alternative activated immunosuppressive M2 state, a clear correlation between their secretion by KRAS mutated cancer and macrophage polarization has not been established." (PMID 33777798, 2021). "Additionally, mutant KRAS results in the autonomous release of type I cytokine complexes by cancer cells." (PMID 34638560, 2021).
cancer (continued). "As it has widely been described, several clinical trials have shown that KRAS mutations in cancer involve a lack of response to targeted anti-epidermal growth factor receptor (EGFR)-based therapies." (PMID 33664850, 2021). "Importantly, the inhibition of cell growth was observed even under a full growth condition for these cancer cell lines; these cells were indeed addicted to the expression of the KRAS or BRAF oncogene for their cell growth." (PMID 33793658, 2021). "Among the top-ranked PRC2+-CGI-enriched pathways, some were shared across multiple cancer types, including “Epithelial mesenchymal transition (EMT)”, “KRAS signaling up”, and “TNFα signaling via NF-KB” pathways, while others such as “Estrogen response early” were specific to a single cancer type." (PMID 33931649, 2021). "The top amplified cancer genes were KRAS, CDK4, BRAF, IL6, TLK2 and MITF." (PMID 34313788, 2021). "Oncogenic KRAS mutations were found in the absence of EGFR mutations in different histological cancer subtypes and in one case of an OSP." (PMID 34885191, 2021). "KRAS is considered a proto-oncogene, with mutant KRAS a common driver of cancer." (PMID 33869008, 2021). "We detail here the DNA replication stress phenotype that associates with oncogenic KRAS in isogenic and non-isogenic cancer cell line models." (PMID 33574444, 2021). "Interestingly, YAP1 has been shown to be involved in both oncogenic KRAS-dependent and KRAS-independent cancer-promoting activities." (PMID 34094936, 2021). "•We synthesized new drug, CCT3833, that inhibits both RAF and SRC, and so may be effective in KRAS-mutant cancers." (PMID 33130216, 2021). "Although the cross-talk between β-catenin and KRAS has been reported to promote cancer metastasis, the functional role of RGL2 remains largely unknown." (PMID 33917100, 2021). "ALKBH5 demethylated and stabilized m6A modification target oncogenes in KRAS mutant cancers, which may influence how vulnerable the cancer is to therapy." (PMID 34016959, 2021). "The samples with missing clinical information were removed, the samples with the KRAS mutation phenotype were integrated, and finally, the data for 177 cancer samples were obtained, which included 128 KRAS mutation samples and 49 non-mutation samples." (PMID 34134622, 2021). "The therapeutic potential of targeting mKRAS as a cancer neoantigen was highlighted in a case report demonstrating clinical benefit in a patient with KRAS G12D metastatic CRC following the adoptive transfer of KRAS G12D-specific T cells restricted to HLA-C*08:0222." (PMID 34272369, 2021). "Thus, CCT3833 inhibits both CRAF and SRC in KRAS-mutant cancers and so we investigate the contribution of these two activities to the inhibition of long-term cell growth." (PMID 33130216, 2021). "Of these comutation events, the NRAS mutations were mostly at codon 61, common for NRAS-driven cancers, such as skin cutaneous melanoma, and there was no detectable pattern of comutation between particular KRAS and NRAS alleles." (PMID 33753749, 2021). "It will be interesting to learn if Phafin2 cooperates with KRAS* to enhance macropinocytosis or if amplification of Phafin2 could provide an alternative, independent way for cancer cells to upregulate nutrient scavenging by macropinosome formation." (PMID 34772942, 2021). "KRAS is one of the most frequently mutated oncogenes in CRC, and mutant KRAS oncoprotein can activate downstream RAF/MEK/ERK and PI3K/AKT signals, which are responsible for cancer cell proliferation, survival, and evasion of apoptosis." (PMID 34347396, 2021).